CRIP1 (cysteine rich protein 1)
Description:
Seems to have a role in zinc absorption and may function as an intracellular zinc transport protein.
Synonyms: CRP-1; CRHP; CRIP; CRP1
Tractability: Antibody: the Human Protein Atlas places it where antibodies can reach. PROTAC: ubiquitination databases record sites on it; its protein half-life has been measured.
Gene: Protein-coding gene on chromosome 14 (105,484,603 to 105,488,947, forward strand). Ensembl gene ENSG00000213145.
Subcellular location (Human Protein Atlas): Cytosol; Nuclear speckles; Centrosome; Plasma membrane
Gene Ontology:
Molecular function: peptide binding; zinc ion binding
Biological process: cellular response to antibiotic; cellular response to UV-B; immune response; intrinsic apoptotic signaling pathway in response to DNA damage; prostate gland stromal morphogenesis; regulation of gene expression; response to zinc ion; heart development
Cellular component: cytoplasm
Genetic constraint (gnomAD): Loss-of-function variants: 11 observed, 12.54 expected, observed/expected ratio (o/e) 0.88, 90% interval 0.55 to 1.45. The upper end of that interval is the gene's LOEUF score, 1.45, which puts it in group 5 of 6, group 1 being the genes least tolerant of losing a copy. Missense variants: 122 observed, 102.16 expected, observed/expected ratio (o/e) 1.19, 90% interval 1.03 to 1.39. Synonymous variants: 41 observed, 37.73 expected, observed/expected ratio (o/e) 1.09, 90% interval 0.85 to 1.41.
Homologues: Orthologues: chimpanzee CRIP1 (100% identical), macaque CRIP1 (100% identical), dog CRIP1 (97% identical), mouse Crip1 (97% identical), rat Crip1 (97% identical), tropical clawed frog crip1 (74% identical). Paralogues in human: CRIP2 (68% identical), CRIP3 (56% identical), LHX9 (30% identical), ZFHX4 (30% identical), LHX2 (27% identical), LMX1A (27% identical), LMX1B (27% identical), ZFHX2 (27% identical), ZFHX3 (27% identical), LHX1 (26% identical), LHX6 (26% identical), FHL1 (25% identical), and 8 more.
Diseases named in the same sentence as CRIP1 in open-access papers:
CRIP1 is named in the same sentence as 60 diseases in open-access papers, as found by Europe PMC text mining. Sharing a sentence is not in itself a finding about the gene and the disease. The quoted sentences say what the papers report.
breast carcinoma (15 papers, 2011 to 2025). "Human breast cancer and cervical carcinomas are associated with increased expression of CRIP1, a member of the LIM/double zinc finger protein family." (PMID 36476230, 2022). "However, in breast cancer, the methylation frequency of CRIP1 increases with the increase of breast cancer tumor stage, and its hypermethylation is associated with poor clinical prognosis." (PMID 40118853, 2025). "However, in agreement with our observations, a high CRIP1 expression in human breast cancer was associated with a better prognosis, and KD of CRIP1 increased the invasive potential of breast cancer cells in vitro, suggesting cell-type-specific functions of CRIP1." (PMID 37390825, 2023). "Studies have found that CRIP1 knockdown increases the invasive potential of breast cancer cells in vitro, promotes cell proliferation, and indicates a good prognosis when highly expressed." (PMID 40118853, 2025). "CRIP1 is downregulated in breast cancer and osteosarcoma, which indicates a higher survival rate and is a marker for predicting good prognosis." (PMID 40118853, 2025). "As a tumor suppressor, CRIP1 is slightly expressed in breast cancer, and matrix metalloproteinase increases after downregulation, showing greater invasive potential." (PMID 40118853, 2025). "Conversely, CRIP1 is a cysteine-rich protein that exhibits aberrant expression in multiple malignancies, including breast cancer, cervical cancer, and pancreatic carcinoma." (PMID 41357233, 2025). "Then, we developed a risk prognostic model based on expression levels of PIK3CA, SESN3, ANXA5, MYD88, DPP4, DAXX, and CRIP1 to predict clinical outcomes in patients with breast cancer." (PMID 41357233, 2025). "In breast cancer, patients with low CRIP1 expression have a poor prognosis, while in gastric cancer, high CRIP1 expression is an independent predictor of adverse prognosis." (PMID 37766321, 2023). "Heat shock protein 1B, NOB1 and CRIP1 were upregulated while BCLAF1 was downregulated in breast cancer after sublethal heat treatment." (PMID 35150481, 2022). "In contrast, CRIP1 expression led to a favourable outcome and fewer metastases in osteosarcoma and breast cancer." (PMID 34413913, 2021). "Further, a peptide targeting the breast cancer biomarker cysteine-rich intestinal protein 1 (CRIP1) showed an IC50 value of 8.8 μM." (PMID 32380649, 2020). "High expression of CRIP1 is correlated with a favorable prognosis in osteosarcoma and breast cancer." (PMID 30850009, 2019). "Although CRIP1 have been studied in various cancer types including prostate cancer, pancreatic caner, cervical cancer, breast cancer, osteosarcoma, thyoid carcinoma and gastric cancer." (PMID 30850009, 2019). "Aberrant expression of CRIP1 was also mentioned in several tumor types including prostate cancer, pancreatic caner, cervical cancer, breast cancer, osteosarcoma, gastric cancer, and thyroid cancer." (PMID 30850009, 2019). "In several studies, CRIP1 has been proposed as a novel biomarker for breast cancer and its precursor lesions which can be triggered by ERBB2 overexpression." (PMID 22202598, 2011). "CRIP1 may be used as a serum biomarker in patients with breast cancer to assist in molecular typing." (PMID 40118853, 2025). "In breast cancer and osteosarcoma, reducing CRIP1 levels may increase cell proliferation, activate cell growth, increase invasion in vitro, and be associated with a worse prognosis." (PMID 40118853, 2025). "In addition to PD-L1, we explored the potential association between CRIP1 and human epidermal growth factor receptor 2 (HER2), a key breast cancer target." (PMID 40118853, 2025). "CRIP1 participates in regulation of proliferation, migration and invasion of breast cancer cells." (PMID 35150481, 2022). "CRIP1 was also identified as a bone specific breast cancer metastasis gene." (PMID 30850009, 2019).
breast carcinoma (continued). "Additionally, a role in ERBB2-related oncogenesis was proposed for CRIP1 since upregulation of CRIP1 was recorded in ERBB2-overexpressing carcinomas of the breast which generally follow an aggressive course." (PMID 22202598, 2011). "Also cysteine-rich intestinal protein 1 (CRIP1), an early marker of mammary carcinoma was up-regulated as a consequence of Tcfap2c upregulation." (PMID 21779369, 2011). "Our study first identified CRIP1 might participate breast cancer progression through m6A manner." (PMID 41357233, 2025). "However, in breast cancer patients, low CRIP1 expression could enhance cell proliferation and invasion by enhancing the mitogen-activated protein kinase phosphorylation and reducing the CDC2 phosphorylation." (PMID 35938037, 2022). "In addition, knockdown of CRIP1 increased breast cancer cell invasion in vitro." (PMID 30850009, 2019). "Interestingly, CRIP1 was also considered a bone-specific breast cancer metastasis gene." (PMID 22202598, 2011). "Based on imaging mass spectrometry analysis, Rauser’s study found that CRIP1 and HER2 show co-expression or highly correlated spatial distribution in tissues, and CRIP1 is significantly upregulated in HER2-positive breast cancer." (PMID 40118853, 2025). "The combination of CRIP1-targeted drugs and anti-HER2-targeted therapies, such as trastuzumab, will bring greater clinical benefit to patients with HER2-positive breast cancer." (PMID 40118853, 2025). "CRIP1 is a member of the CRIP protein subfamily, which is considered as a new biomarker of osteosarcoma, prostate cancer and breast cancer." (PMID 35150481, 2022). "Recently, CRIP1, with only one LIM domain, has been studied in several malignancies including colorectal cancer, breast cancer, cervical cancer, and osteosarcoma." (PMID 34413913, 2021). "Moreover, the expression levels of SESN3, CRIP1, DPP4 and PIK3CA were significantly upregulated in breast cancer samples compared to control samples." (PMID 41357233, 2025). "Knockdown of CRIP1 inhibited the proliferation of thyroid carcinoma cells through inducing G1 arrest and apoptosis, while silencing of CRIP1 significantly elevated the proliferation of T47D and BT474 breast cancer cells via reducing the phosphorylation of cdc2." (PMID 30850009, 2019).
cervical carcinoma (10 papers, 2008 to 2025). A carcinoma arising from either the exocervical squamous epithelium or the endocervical glandular epithelium. "Compared with adjacent normal tissues, CRIP1 was significantly more highly expressed in cervical cancer and was associated with FIGO stage." (PMID 34261404, 2021). "The overexpression of CRIP1 has been observed in several human malignant tumors, including cervical cancer, breast cancer, prostate cancer, colorectal cancer, pancreatic cancer, gastric cancer and osteosarcoma." (PMID 23570421, 2013). "Recently CRIP1 has been identified as a very exciting biomarker for human breast cancers,4, cervical cancers, pancreatic cancers and potentially other cancers." (PMID 18670594, 2008). "CRIP1 is involved in carnitine metabolism and cancer stem-like properties in hepatocellular carcinoma; DNA methylation in prostate cancer; and cell migration, invasion, and the epithelial–mesenchymal transition in cervical cancer." (PMID 37766321, 2023). "CRIP1 overexpression has also been demonstrated to be the most highly differentially expressed gene in invasive cervical carcinomas; 100-fold up-regulation relative to normal cervical keratinocytes measured in 34 cervical tissues from different clinically defined stages." (PMID 18670594, 2008). "Although one study has discovered the mechanism of CRIP1 in cervical cancer at present, it has not been studied in depth in other gynecological tumors." (PMID 35140819, 2022).
gastric cancer (10 papers, 2013 to 2025). A primary or metastatic malignant neoplasm involving the stomach. "Simply put, CRIP1 is overexpressed in gastric cancer and CRIP1 deficiency inhibits the process of homologous recombination and increases susceptibility to chemotherapy in gastric cancer cells." (PMID 35720327, 2022). "Studies in gastric cancers have demonstrated that CRIP1 expression is directly associated with a worse prognosis for patients." (PMID 23570421, 2013). "Through the reciprocal effects of VEGFC and CCL5, CRIP1 can promote lymphangiogenesis and lymphatic metastasis development in gastric cancer." (PMID 37409440, 2023). "A previous study on the role of CRIP1 can well explain the protective role of FBXO5 in gastric cancer." (PMID 35720327, 2022). "FBXO5 can block CRIP1-promoted homologous recombination repair by preventing nuclear enrichment of RAD51, thereby restoring chemotherapy sensitivity of gastric cancer cells with high CRIP1 expression." (PMID 35720327, 2022). "In conclusion, our study suggests an essential function of CRIP1 in promoting HR repair and facilitating gastric cancer cell adaptation to genotoxic therapy." (PMID 34262130, 2021). "In gastric cancer, CRIP1 was overexpressed in primary tumor tissues and confirmed to be an independent prognostic factor." (PMID 34261404, 2021). "In contrast, high CRIP1 expression was confirmed as a novel and independent prognostic factor for poor prognosis in gastric cancer patients." (PMID 30850009, 2019). "A recent study on an intestinal type of gastric cancer reported that the overexpression of CRIP1 was an independent predictor of shortened survival." (PMID 23570421, 2013). "In TME of gastric cancer, overexpression of cysteine-rich intestinal protein-1 (CRIP1) induces lymphangiogenesis and lymphatic permeability, and then facilitates lymphatic metastasis by upregulating expression of VEGF-C and C-C motif chemokine ligand 5 (CCL5) signaling." (PMID 41511312, 2025). "In gastric cancer, CRIP1 interacts with cAMP response element binding protein 1 for transcription to promote the expression of C-C motif chemokine ligand 5 (CCL5), recruit macrophages to promote the secretion of TNF-α, and finally enhance lymphatic permeability to cause tumor cell migration." (PMID 40118853, 2025). "Here we found that CRIP1 downregulation causes HR repair deficiency with concomitant increase in cell sensitivity to cisplatin, epirubicin, and the poly ADP-ribose polymerase (PARP) inhibitor olaparib in gastric cancer cells." (PMID 34262130, 2021). "Patients with gastric carcinoma overexpressing CRIP1 had shorter overall survival." (PMID 34261404, 2021). "However, the inverse prognostic relevance of CRIP1 expression that we identified in our tumor cohort is not in agreement with results obtained in gastric cancers." (PMID 23570421, 2013). "Due to the negative correlation between CRIP1 expression and survival time in gastric cancer patients, FBXO5 may exhibit a potential protective role in the prognosis of gastric cancer through inhibiting the identified function of CRIP1 in this report." (PMID 35720327, 2022).
ovarian cancer (7 papers, 2021 to 2025). A primary or metastatic malignant neoplasm involving the ovary. "The increase in CRIP1 level is associated with prognosis and immune cell infiltration in patients with ovarian cancer and sarcoma." (PMID 40118853, 2025). "Here, we revealed the function of CRIP1 in ovarian cancer and its underlying mechanism for the first time." (PMID 34413913, 2021). "We further explored the role of CRIP1 in ovarian cancer by qRT-PCR and western blot in the OC cell line." (PMID 35140819, 2022). "To verify the expression of CRIP1 in ovarian cancer, we selected two ovarian cancer cell lines (A2780 and OVCAR3) and used the normal ovarian cell line IOSE80 as the control." (PMID 34413913, 2021). "To explore the biological pathways by which CRIP1 is involved in ovarian cancer pathogenesis, we further conducted KEGG pathway enrichment analysis." (PMID 34413913, 2021). "First, we used bioinformatics methods to screen out the oncogene CRIP1 in ovarian cancer from the TCGA database, showing that ovarian cancer with the high expression of CRIP1 had a poor prognosis." (PMID 34413913, 2021). "In this study, our objective was to describe CRIP1 expression patterns, functions, and possible mechanisms in ovarian cancer." (PMID 34413913, 2021). "To determine the role of CRIP1 in ovarian cancer, we knocked down CRIP1 in OVCAR3 cells using three different short interfering RNAs (siRNAs), including si-168, si-229, and si-276." (PMID 34413913, 2021). "We observed the same trend; i.e., that CRIP1 had a markedly higher expression level in ovarian cancer tissues than in normal samples, suggesting an oncogenic property of CRIP1." (PMID 34413913, 2021). "Next, we demonstrated CRIP1 expression in ovarian cancer and its relationship with disease." (PMID 34413913, 2021). "Further research revealed that elevated CRIP1 was closely correlated with a higher pathological stage, grade, and positive lymphatic metastasis of patients, pointing to a link between increased CRIP1 expression and ovarian cancer aggressiveness." (PMID 34413913, 2021). "However, this study only validated the effect of CRIP1 on the ovarian cancer OVCAR3 cell line at the cellular level." (PMID 34413913, 2021). "Furthermore, the CRIP1 content in ovarian cancer tissues was detected by immunohistochemistry (IHC), including 26 pairs of serous epithelial ovarian cancer tissues with matched adjacent normal tissues." (PMID 34413913, 2021). "The results show that the upregulation of CRIP1 can promote ovarian cancer invasion, metastasis, and EMT by activating the Wnt signaling pathway, suggesting that CRIP1 could be viewed as a valuable new biomarker for ovarian cancer." (PMID 34413913, 2021). "Our results confirm that β-catenin had relatively high expression in ovarian cancer cells but was downregulated when CRIP1 was knocked down, suggesting that CRIP1 may activate β-catenin." (PMID 34413913, 2021). "Furthermore, KEGG pathway enrichment analysis and western blot were conducted to reveal the signaling pathways in which CRIP1 is involved in ovarian cancer pathogenesis." (PMID 34413913, 2021). "Interestingly, the violin plot shows that CRIP1 expression increased with an increase in tumour pathological stage, suggesting a close positive correlation between CRIP1 expression and ovarian cancer grade (F = 6.34, P < 0.05)." (PMID 34413913, 2021). "Furthermore, additional ovarian cancer cell lines, overexpression cell models, and animal models (in vivo) are required to confirm the links between CRIP1 expression and ovarian cancer progression and prognosis." (PMID 34413913, 2021). "CRIP1 is negatively correlated with Th2 and natural killer cells in patients with ovarian cancer, suggesting that patients with tumors having high CRIP1 expression may have immunosuppression; gene enrichment shows that it may be related to abnormal activation of JAK/STAT signaling pathway." (PMID 40118853, 2025).
ovarian cancer (continued). "Therefore, our findings indicate that EMT may be an indispensable process for CRIP1-mediated ovarian cancer invasion and metastasis." (PMID 34413913, 2021). "Furthermore, KEGG pathway enrichment analysis and western blot showed that CRIP1 could induce ovarian cancer cell metastasis through activation of the Wnt/β-catenin pathway." (PMID 34413913, 2021). "In particular, this process may be achieved through the Wnt/β-catenin signaling pathway by inducing EMT, suggesting that CRIP1 may be an important biomarker for ovarian cancer metastasis and prognosis, as well as an important molecular target for ovarian cancer therapy." (PMID 34413913, 2021). "Combined with the results of cell function experiments, we deduced that CRIP1 is involved in the process of cell migration and invasion by regulating EMT in ovarian cancer." (PMID 34413913, 2021). "The results showed no significant change in proliferation and apoptosis in ovarian cancer cells, which was consistent with a recently published study on CRIP1-depleted colorectal cancer cells." (PMID 34413913, 2021). "We confirmed a high level of expression of CRIP1 in OVCAR3 and ovarian cancer tissues." (PMID 34413913, 2021). "The box plot shows the significantly upregulated expression of CRIP1 in ovarian cancer tissues compared with adjacent nonneoplastic tissues (∣log2 FC∣ cut-off: 1, P value; cut-off: 0.01, P < 0.05)." (PMID 34413913, 2021). "Indeed, in our study, the level of p-GSK-3β, but not total GSK-3β, was downregulated in ovarian cancer when CRIP1 was silenced." (PMID 34413913, 2021). "Moreover, the relationship between ovarian cancer and CRIP1 has not yet been discussed." (PMID 34413913, 2021). "Our data showed that high CRIP1 expression was closely related to higher pathological stage, grade, and positive lymphatic metastasis, whereas no relation was detected with age, tumour diameter, or CA125 level, indicating that CRIP1 may promote ovarian cancer aggressiveness and distant metastasis." (PMID 34413913, 2021). "This study is the first to demonstrate that CRIP1 acts as an oncogene and may promote tumour metastasis by regulating the EMT-related Wnt/β-catenin signaling pathway, suggesting that CRIP1 may be an important biomarker for ovarian cancer metastasis and progression." (PMID 34413913, 2021).